MED6 (mediator complex subunit 6)
Description:
Component of the Mediator complex, a coactivator involved in the regulated transcription of nearly all RNA polymerase II-dependent genes. Mediator functions as a bridge to convey information from gene-specific regulatory proteins to the basal RNA polymerase II transcription machinery. Mediator is recruited to promoters by direct interactions with regulatory proteins and serves as a scaffold for the assembly of a functional preinitiation complex with RNA polymerase II and the general transcription factors.
Synonyms: ARC33; NY-REN-28
Tractability: Small molecule: a structure with a bound ligand is known. PROTAC: UniProt records ubiquitination sites on it; ubiquitination databases record sites on it; its protein half-life has been measured.
Gene: Protein-coding gene on chromosome 14 (70,581,257 to 70,600,690, reverse strand). Ensembl gene ENSG00000133997.
Subcellular location: Nucleus
Subcellular location (Human Protein Atlas): Nucleoplasm
Pathways (Reactome):
Gene expression (Transcription): Generic Transcription Pathway; MLL4 and MLL3 complexes regulate expression of PPARG target genes in adipogenesis and hepatic steatosis
Developmental Biology: Transcriptional regulation of white adipocyte differentiation
Disease: RSV-host interactions
Metabolism: PPARA activates gene expression
Gene Ontology:
Molecular function: protein binding; transcription coactivator activity; transcription coactivator binding; DNA binding; transcription coregulator activity
Biological process: positive regulation of transcription by RNA polymerase II; positive regulation of transcription elongation by RNA polymerase II; positive regulation of transcription initiation by RNA polymerase II; regulation of transcription by RNA polymerase II; RNA polymerase II preinitiation complex assembly
Cellular component: core mediator complex; mediator complex; membrane; nucleoplasm; nucleus
Genetic constraint (gnomAD): Loss-of-function variants: 24 observed, 27.37 expected, observed/expected ratio (o/e) 0.88, 90% interval 0.63 to 1.23. The upper end of that interval is the gene's LOEUF score, 1.23, which puts it in group 5 of 6, group 1 being the genes least tolerant of losing a copy. Missense variants: 198 observed, 256.11 expected, observed/expected ratio (o/e) 0.77, 90% interval 0.69 to 0.87. Synonymous variants: 89 observed, 83.39 expected, observed/expected ratio (o/e) 1.07, 90% interval 0.9 to 1.27.
Homologues: Orthologues: chimpanzee MED6 (99% identical), macaque MED6 (98% identical), dog MED6 (96% identical), rabbit MED6 (96% identical), mouse Med6 (95% identical), pig MED6 (95% identical), guinea pig MED6 (95% identical), rat Med6 (94% identical), tropical clawed frog med6 (87% identical), zebrafish med6 (78% identical), Drosophila melanogaster MED6 (46% identical), Caenorhabditis elegans mdt-6 (34% identical).
Diseases named in the same sentence as MED6 in open-access papers:
MED6 is named in the same sentence as 5 diseases in open-access papers, as found by Europe PMC text mining. Sharing a sentence is not in itself a finding about the gene and the disease. The quoted sentences say what the papers report.
colitis (1 paper, 2025). Inflammation of the colon. "Of the WT‐enriched proteins, three were also enriched in naïve colons, including Cpt1b, Med6, and Serpina1d, while the remaining 34 upregulated proteins were only significant in the inflamed colon and may represent proteins affected by the increased legumain activity associated with colitis." (PMID 40970443, 2025).
tumor (4 papers, 2014 to 2025). "In over 80% of these lines, MED6 knockout significantly inhibited tumor cell growth, indicating that MED6 is closely linked to tumor cell proliferation and growth." (PMID 40302793, 2025). "Additionally, other Mediator subunits have been linked to tumor pathology and prognosis 65, 66, reinforcing the potential of MED6 as a key player in tumor biology." (PMID 40302793, 2025). "Although different types of SEMA have distinct roles in angiogenesis 90, 91, this highlights the complex role of MED6 in tumor biology." (PMID 40302793, 2025). "Further in vivo and in vitro studies are needed to validate the role of MED6 in LUAD tumor cells and its downstream effects." (PMID 40302793, 2025). "Building on the advantages of bioinformatics technologies in cancer research 46, 76, 77, our study explored how MED6 affects interactions between tumor cells and other cells in TME at the single-cell level." (PMID 40302793, 2025). "Even in pathways related to angiogenesis, invasion, metastasis, and immune suppression—such as VEGF, PDGF, and TGF-β83-85—MED6-positive tumor cells showed stronger intercellular communication." (PMID 40302793, 2025). "Compared to MED6-negative tumor cells, MED6-positive tumor cells showed more frequent interactions with other TME cell types." (PMID 40302793, 2025). "Our results suggest that MED6 promotes tumor progression by influencing tumor cell proliferation and intercellular interactions within the TME, thereby impacting LUAD prognosis." (PMID 40302793, 2025). "Our results showed that MED6-positive tumor cells exhibited more significant activity in interactions with stromal and immune cells via secreted signals like SEMA, MDK, and SPP1." (PMID 40302793, 2025). "In our study, we identified MED6 through tumor cell proliferation assays and differential expression analysis in LUAD." (PMID 40302793, 2025). "Given the potential role of MED6 in LUAD tumor progression, we performed drug screening for MED6-high-expressing populations." (PMID 40302793, 2025). "By integrating single-cell sequencing and RNA-seq data, we found that MED6 may interact with other cells in the tumor microenvironment." (PMID 40302793, 2025). "In conclusion, MED6 may regulate tumor cell interactions in the TME, contributing to tumor progression." (PMID 40302793, 2025). "Additionally, the mechanisms behind MED6-positive tumor cell interactions in the TME require further investigation." (PMID 40302793, 2025). "Single-cell analysis was performed to investigate the role of MED6 in tumor cells." (PMID 40302793, 2025). "Notably, the EMT pathway, which is critical for tumorigenesis and metastasis, was also enriched in the MED6-high-expression group 75, suggesting that high MED6 levels may facilitate tumor invasion and metastasis." (PMID 40302793, 2025). "Additionally, the epithelial-mesenchymal transition (EMT) pathway was upregulated in the MED6-high group, suggesting that MED6 may enhance tumor cell motility and migration." (PMID 40302793, 2025). "In summary, MED6 likely promotes LUAD progression by regulating downstream gene expression and tumor cell growth." (PMID 40302793, 2025). "MED6-positive tumor cells showed more active interactions with other cells in the LUAD microenvironment, promoting tumor progression." (PMID 40302793, 2025). "MED6 exhibited the lowest CERES score and the highest dependency for cell growth, indicating that it is more critical for tumor proliferation than the other genes." (PMID 40302793, 2025). "Among them, only three genes—MED6, MED14, and MED20—were found to be highly expressed in LUAD and essential for tumor cell growth." (PMID 40302793, 2025). "TWIST1 protein expression was also assessed in primary tumor samples corresponding to the MED1 and MED6 cell lines." (PMID 33948561, 2021). "MED5R and MED6 are derived from WNT subtypes (β-catenin positive) large cell anaplastic and classical tumours respectively." (PMID 24887326, 2014).
tumor (continued). "Based on MED6 expression, tumor cells were divided into MED6-positive and MED6-negative cells, resulting in 10 distinct cell types." (PMID 40302793, 2025).
cancer (2 papers, 2012 to 2025). A tumor composed of atypical neoplastic, often pleomorphic cells that invade other tissues. "The genes categorized into “cancer” group by IPA biofunctions analysis were GPX1, HDAC7, PSME2, MED6, GOLPH3 and MST4 (p<0.05)." (PMID 22438889, 2012).
MED6 also shares sentences with these, for which no sentence is quoted: lung adenocarcinoma (1 paper); lung carcinoma (1).